KCNH4 (potassium voltage-gated channel subfamily H member 4)
Description:
Pore-forming (alpha) subunit of a voltage-gated delayed rectifier. Activates at more negative voltages, exhibits fast prepulse-independent activation kinetics and deactivates much more slowly, but shows no inactivation (By similarity).
Synonyms: BEC2; ELK1; Kv12.3
Tractability: Small molecule: an approved drug acts on it; it belongs to a druggable protein family. Antibody: its Gene Ontology location is reachable by antibodies, with high confidence; UniProt predicts a signal peptide or a membrane-spanning region.
Gene: Protein-coding gene on chromosome 17 (42,156,891 to 42,181,142, reverse strand). Ensembl gene ENSG00000089558.
Subcellular location: Membrane
Pathways (Reactome):
Neuronal System: Voltage gated Potassium channels
Gene Ontology:
Molecular function: voltage-gated potassium channel activity; monoatomic ion channel activity
Biological process: potassium ion transmembrane transport; potassium ion transport; regulation of membrane potential; monoatomic ion transport; transmembrane transport
Cellular component: plasma membrane; voltage-gated potassium channel complex; membrane
Genetic constraint (gnomAD): Loss-of-function variants: 32 observed, 85.95 expected, observed/expected ratio (o/e) 0.37, 90% interval 0.28 to 0.5. The upper end of that interval is the gene's LOEUF score, 0.5, which puts it in group 2 of 6, group 1 being the genes least tolerant of losing a copy. Missense variants: 1,025 observed, 1,367.8 expected, observed/expected ratio (o/e) 0.75, 90% interval 0.71 to 0.79. Synonymous variants: 542 observed, 579.93 expected, observed/expected ratio (o/e) 0.93, 90% interval 0.87 to 1.
Homologues: Orthologues: chimpanzee KCNH4 (99% identical), macaque KCNH4 (98% identical), pig KCNH4 (93% identical), dog KCNH4 (93% identical), mouse Kcnh4 (90% identical), rat Kcnh4 (86% identical), guinea pig KCNH4 (80% identical), rabbit KCNH4 (80% identical), tropical clawed frog kcnh4 (61% identical), zebrafish kcnh4b (59% identical), zebrafish kcnh4a (58% identical), Drosophila melanogaster Elk (45% identical), and 10 more. Paralogues in human: KCNH8 (57% identical), KCNH3 (49% identical), KCNH2 (37% identical), KCNH7 (35% identical), KCNH6 (34% identical), KCNH1 (30% identical), KCNH5 (29% identical), HCN4 (17% identical), HCN2 (17% identical), HCN1 (16% identical), HCN3 (15% identical), CNGB1 (14% identical), and 5 more.
Diseases named in the same sentence as KCNH4 in open-access papers:
KCNH4 is named in the same sentence as 2 diseases in open-access papers, as found by Europe PMC text mining. Sharing a sentence is not in itself a finding about the gene and the disease.
KCNH4 shares sentences with these, for which no sentence is quoted: gynecological cancers (1 paper); malignant melanoma (1).